TGFB2 (transforming growth factor beta 2)
Diseases named in the same sentence as TGFB2 in open-access papers (continued):
Sharing a sentence is not in itself a finding about the gene and the disease.
cancer (continued). "Several genes associated with cancer cell motility, including SEMA5A, PDGFRB, TGFB2, CXCR4, SNAI1, ICAM1, and NEDD9, were decreased in shGPR81 cells." (PMID 35428832, 2022). "Other top genes overlapping with significant CpGs include PLD2 (cancer development and progression), and TGFB2 (regulation of angiogenesis and heart development)." (PMID 36457128, 2022). "Recently, a molecule that simultaneously inhibited TGFB2 and PD-L1 expression was reported and showed high efficacy in cancer treatment." (PMID 34344966, 2021). "Intriguingly, we observed an increase in glycolytic capacity and reserve following TGFβ2 treatment which was accompanied by an increased expression of glycolytic enzymes, PFKFB3, PKM2 and LDHA, linked to EMT in cancer metastasis models." (PMID 33946753, 2021). "We also found a positive correlation between ABCC4 expression and TGFβ1/2 receptors and its ligand TGFβ2, which were shown to be involved in epithelial conversion induction in cancers." (PMID 33261018, 2020). "Our study collectively provides evidence on the functional and clinical significance of TGFβ2 and the potential of imperatorin as novel therapeutic strategy for cancer treatment." (PMID 32832354, 2020). "We next explored the link between the expression of TGFβ2 and cancer patient outcome using the PrognoScan database." (PMID 32530106, 2020). "Taken together, these data indicated that imperatorin inactivates TGFβ2‐ERK signaling to inhibit cancer invasion." (PMID 32832354, 2020). "Our results showed that blockade of MEK pathway with U0126 significantly abrogated the promoting effect of TGFβ2 on cancer cell invasion and EMT phenotype." (PMID 32832354, 2020). "An additional key finding in this study is that the expression of TGFβ2 correlated with the degree of immune infiltration in multiple cancer types, and particularly in GC." (PMID 32530106, 2020). "In this study, we found that TGFβ2 expression correlated with patient prognosis in several types of cancer, with a particularly strong correlation between high TGFβ2 expression and a poor STAD prognosis." (PMID 32530106, 2020). "We further used the GEPIA database to assess how TGFΒ2 expression relates to patient prognosis, analysing 33 TCGA cancer types and revealing that TGFβ2 expression correlated both with OS and DFS in ACC, LGG, STAD (Figure [Link], [Link], [Link])." (PMID 32530106, 2020). "Blockade of TGF-β2 signaling reduced plasma membrane-associated CD36 expression and using a fluorescent palmitate analog (BODIPY-conjugated C16), we confirmed the increased capacity of FA uptake by TGFβ2-stimulated native cancer cells." (PMID 31974393, 2020). "In line with this study, 43 genes (including CLIP4) were downregulated in ovarian cancer tumor samples and reactivated after treatment with 5-Aza-2'-deoxycytidine (5-aza-dC); CLIP4, GULP1, BAMBI, NT5E, and TGFB2 showed a pattern of cancer-specific methylation." (PMID 33575272, 2020). "Recently, it has been shown that transforming growth factor β2 (TGFβ2) activates p38 in cancer cells disseminated to bone inducing dormancy." (PMID 31484342, 2019). "In this regard, an up-regulation of TGFβ2 and p27 expression induced by hypoxia has been shown in dormant cancer cells, confirming a key role of hypoxia on dormancy." (PMID 31484342, 2019). "For example, mutations in genes such as PTEN, SMAD2, TGFB2, and SRC implicated in epithelial-mesenchymal transition, metastasis, and cancer progression, were enriched in more aggressive groups while the other genes clustered in the less aggressive groups." (PMID 28007036, 2016). "Together with OVCA432 and MCAS, the three cancer cell lines showed essentially much lower TGFβ2 expression compared with the OSE cells." (PMID 26684027, 2016). "qRT-PCR has confirmed elevated expression of miR-200 family in the cancer 3D models, which was also consistent with the elevated expression of E-cadherin and downregulation of TGFβ2 in the cancer cells." (PMID 26684027, 2016).
cancer (continued). "TGFB2 has an intronic Alu repeat that was hypomethylated in some cancer cell lines when compared to various normal tissues." (PMID 25606572, 2014). "Antisense oligonucleotides against TGFβ2 have been tested in a number of clinical trials against various cancers, with promising results." (PMID 20836854, 2010). "The TGFβ family of cytokines has been shown to promote EMT during cancer progression and this is in accordance with the present study showing a strong down-regulation of Tgfβ1, Tgfβ2 and the receptors Tgfβr1 and 2 after HBO treatment." (PMID 19636430, 2009). "Tlr4, Vegfa, Tgfb2 are from MMU5205 (Proteoglycans in cancer)." (PMID 39789452, 2025). "So, the Cacna1d, Kcnj12 Tgfb2, Cav1, Mecom, Kitlg, and Bmp2 genes had associations with any of the five pathways of PC1 (glutamatergic synapse, cholinergic synapse, proteoglycans in cancer, pathways in cancer, and MAPK signaling pathway)." (PMID 40076966, 2025). "Although the biological roles of TGFβ signalling have been widely studied, the regulation of TGFβ2 expression in cancer remains unclear." (PMID 38299307, 2024). "The pattern of induced clusters differed between TGFβ2 and CM stimulation, suggesting that CM contains other secreted signaling molecules in addition to TGFβ2 which promote this specific transition and that the TGFβ2-mediated effect requires direct contact between cancer cells and Detox-iCAF." (PMID 38561380, 2024). "Among these, TGFB2 has been extensively studied in airway epithelial remodeling, cell migration, and other biological processes like epithelial–mesenchymal transition in cancer." (PMID 39850030, 2024). "Similarly, by submitting Cancer Therapeutics Response Portal (CTRP) data we found TGFB2 was also involved in lipid metabolism, that is lipid droplet." (PMID 38914663, 2024). "In addition to having an impact on the malignant development of several cancers, TGFB2 has recently been discovered to alter the chemotherapeutic response of cancers." (PMID 38914663, 2024). "Both NPM1 and TGFB2 have been shown to promote cancer cell growth and metastasis, we thus determined whether snoVector‐expressed oncoproteins exert these oncogenic activities." (PMID 37063610, 2023). "However, since the RIP-seq results were also validated with real-time RT-PCR, at least six genes related to “Pathways in cancer,” i.e., TGFB2, CREBBP, EP300, FOS, JUN, and MYC were certainly affected by the hnRNPM-AS1-S interaction." (PMID 37671887, 2023). "In addition, the increased expression of TGFβ2 in a variety of cancers is often positively correlated with epithelial-mesenchymal transition (EMT) and coordinated with the expression of genes related to driving EMT." (PMID 35620459, 2022). "On its side, TGFB2 is a two-faceted cytokine well-known for its ability to, on the one hand, arrest the proliferation of normal cells or of early-stage cancer cells and, on the other hand, enhance tumorigenesis in a number of advanced cancers." (PMID 36494864, 2022). "Collectively, these meta-analyses suggest that in a given tissue, aggregated expression of FN1, TGFBR2, TGFB2, and TGFBI might serve as an index for the extent of cancer-associated fibroblasts (CAFs)." (PMID 32605311, 2020). "Furthermore, the Pathway analysis based on KEGG method indicated that, among the 10 differentially expressed mRNAs, ITGB3, TGFβ2 and TNC were linked to the pathway of MicroRNAs in Cancer." (PMID 33100909, 2020). "Overall, the findings suggest the use of TGFβ2 as a diagnostic and prognostic biomarker and therapeutic target in ESCC, and supports the potential of imperatorin as a novel therapeutic strategy for cancer metastasis." (PMID 32832354, 2020).
cancer (continued). "Altered TGFβ2 expression in a range of different cancers may be due to the different means of data collection in different studies, or it may relate to differences in the underlying biological mechanisms." (PMID 32530106, 2020). "Based on the observation of upregulated EMT and associated key signature genes such as TGFB2, TGFBR2, SMAD2, and ZEB1 in the high-risk patients, we infer that m6A regulatory machinery must interact with EMT to regulate cancer metastasis in various human malignancies." (PMID 31069256, 2019). "Integrated analysis of public databases and structural predictions indicated that the two affected individuals also had additional variants in genes including TGFB2, TRAP1, PARP1, and EGF, each potentially relevant to cancer risk alone or in conjunction with the SDHA variant." (PMID 30680959, 2019). "Interestingly, some clinical trials have been initiated to target ICAM-1 and TGFβ2 individually as the possibilities for future cancer immunotherapies." (PMID 29966014, 2018). "For the upregulation from primary to metastasis fibroblasts by TGFβ1 and TGFβ2, this may be because the role of TGFβ is strongly context-dependent in the metastatic progress, including cell and cancer type." (PMID 29221185, 2017). "In addition, studies have shown that TGFβ2 overexpression promotes motility, invasion and EMT in cells from some cancer types, thus indicating a role for the TGFβ2/Smad signaling pathway in tumorigenesis." (PMID 29110682, 2017). "Future experimental studies may validate the potential role up-regulation of Il-6, Cxcl1, Ctgf, and Tgfb2 may have in promoting cancer cell migration, invasion, and cancer-induced bone metabolism." (PMID 27600237, 2015). "Since our results from 3D spheroids suggest that miR-191 is a major regulator of TGFβ2 levels, thus, targeting miR-191 in tumors may have an added advantage during cancer treatment." (PMID 25867965, 2015). "With respect to the immune system, RFX1 acts as an activator of MHC Class II genes and represses MCP1, CD11a, CD70, IL17A, TLR4, and the TGFβ2 expressions, which could be instrumental in understanding etiology and materializing treatment strategies for cancer and other immune-related disorders." (PMID 33964962, 2021). "Furthermore, TGFB2 played an important role in tumorigenesis and cancer progression, which suggested TGFB2 may be an indicator for identifying ALV-J infections." (PMID 34136553, 2021). "Of all the differentially expressed genes, secreted signaling proteins Tgfb2, Il-6, Cxcl1, and Ctgf and metallopeptidases Mmp13, Adamts4, and Adamts5 were of particular interest, as these genes have previously been shown to play a role in regulating cancer migration and invasion and bone remodeling." (PMID 27600237, 2015). "Here, we show that TGFβ2 is preferentially expressed in mesenchymal‐like BCs and maintains the EMT phenotype, correlating with cancer stem cell‐like characteristics, growth, metastasis and chemo‐resistance and predicting worse clinical outcomes." (PMID 38299307, 2024). "It is reported that TGFB2 was involved in fatty acid metabolism and TGFB2 signaling favored the formation of lipid droplets to support acidosis-driven EMT and the metastatic spreading of cancer cells." (PMID 38914663, 2024). "Notch1 signaling was activated in TGFβ2‐stimulated EMT, and played a significant role in cancer metastasis and recurrence." (PMID 37533228, 2023). "So, downregulation of TGFB2 results in the expression of anti-apoptotic proteins BCL2 and BCL-W, and enhanced cancer cell survival, which confers platinum resistance in NSCLC and 5-FU resistance in CRC cells, respectively." (PMID 37239828, 2023).
cancer (continued). "This PTHrP-IGF/TGFβ2/BMP-PTHrP positive feedback loop represents the canonical process of “vicious cycle”, which tremendously potentiates metastatic cancer cell proliferation and expedites bone remodeling at the metastatic sites." (PMID 37746292, 2023). "Astrocytes can produce transforming growth factor-beta 2 (TGF-β2), which, in turn, regulates SMAD-mediated ANGPTL4 expression in cancer cells, contributing to successful colonization." (PMID 36835266, 2023). "TGFB2 was included in a four gene signature (FN1, TGFB2, TGFBR2, and TGFBI), as an indicator of CAF abundance, which predicted survival in TCGA pan-cancer cohort comprising 9356 patients from 32 cancer subtypes." (PMID 37296997, 2023). "Currently, most cancer and fibrotic EMT are regulated by TGFβ1, while TGFβ2 primarily controls EndMT in the heart development, and TGFβ3 mediates EMT in development." (PMID 36882799, 2023). "We compared the expression level of TGFβ2 in the STAD, GSE29272 and GSE184336 (HMUCH) data sets, and TGFβ2 was expressed at higher levels in cancer tissues than in the adjacent normal tissues (p < 0.01)." (PMID 35620459, 2022). "Currently, several therapies that specifically inhibit TGFB2, such as antisense phosphorothioate oligodeoxynucleotide trabedersen (AP12009), have entered clinical development in patients with advanced cancers." (PMID 36105107, 2022). "ELF3, which is predicted to drive the expression of highly expressed ID genes ANXA3, TGFB2, and duct marker KRT8, has been shown to drive ligand-independent transactivation of CTNNB1 in cancer models." (PMID 36540608, 2022). "Therefore, targeted TGFB2 therapy for cancer patients may be a promising strategy." (PMID 36105107, 2022). "We found ENPEP is correlated with TGF‐β coding genes TGFB1(80%), TGFB2(64%), TGFB3(88%) in most cancers." (PMID 34862755, 2022). "The results also revealed a decrease in KCNA2, SNCG, and TGFB2 levels with a simultaneous increase in GNB1, CXCL12, SNCA, and OPRK1 expression in G2 cancer compared to control." (PMID 34768458, 2021). "RFX1 reduces cancer cell proliferation by targeting FGF1 and transforming growth factor beta 2 (TGFβ2), induce differentiation by targeting CD44 and c-Myc, and promote apoptosis by regulating myeloid cell leukemia sequence 1 protein (MCL1)." (PMID 33964962, 2021). "These genes include known and novel FOXL2 targets (TGFB2, SMARCA4, HSPG2, MKI67, NFKBIA) and are enriched for neoplastic pathways (Proteoglycans in Cancer, Chromatin remodeling, Apoptosis, Tissue Morphogenesis, Tyrosine Kinase Receptors)." (PMID 33639972, 2021). "The expression levels of TGFB2 and TGFB3 were extremely low, while the TGFB1 expressed dominantly in the monocytes in blood and the macrophages in cancer tissues." (PMID 35069521, 2021). "Some of the druggable genes were expected to correlate with non-cancer cells, including the cytokines IL6 and TGFB2, which correlated with epithelial cells and fibroblasts, respectively." (PMID 32275708, 2020). "Quantitative proteomics, IPA analysis and experimental data showed that TGFβ2 mediated the suppressive effects of imperatorin on ERK signaling and cancer invasion." (PMID 32832354, 2020). "Based on RNA-seq data from the cancer cell line encyclopedia, HepG2 cells expressed much higher levels of TGFB1 than TGFB2 or TGFB3." (PMID 31462641, 2019). "This was correlated with an autocrine TGFβ2 upregulation, increased EMT-ness and cancer stemness, arrested cell cycle and cytoskeletal function, and remarkable adaptive transcriptome-metabolome-bioenergetics alterations." (PMID 27852038, 2016). "Consistent with previous reports that cancer cells often exhibit defective ER stress signaling, we found that thapsigargin (TG) treatment enhanced IRE1α and PKAc phosphorylation and upregulated XBP1 target genes such as YBX2 and TGFβ2." (PMID 41516347, 2026).
cancer (continued). "Furthermore, during the osteolytic processes, the growth/osteogenic factors stored in bone matrix, such as IGF, TGFβ2 and BMP, are released, which act back on cancer cells and OBs." (PMID 37746292, 2023). "In addition, 49 EMT related genes, including the TGFβ‐2 mediated SMAD‐EMT‐cancer pathway were reversed by DHA treatments." (PMID 37859621, 2023). "Reports documenting that SRGN promotes cancer cell aggressiveness and metastasis through several signaling pathways, including CD44/NF-κB/CLDN1 axis, HIF-1α/SRGN axis, and SRGN/TGFβ2 axis, may further support our observations presented here." (PMID 34059749, 2021). "In total, 57 candidate compounds, which have not been reported to exert any effect in cancer invasion, was taken and their effect on TGFβ2 expression and cell invasion was determined by using Western blot and Boyden chamber assay, respectively, in ESCC cells." (PMID 32832354, 2020). "Correlational analysis of clinical OSCC datasets with TGFβ axis differentially expressed genes revealed that the summed expression of FN1, TGFB2, TGFBR2, and TGFBI, dubbed as the CAF index, is a powerful predictor in dichotomized survival analysis for patients of diverse cancer subtypes." (PMID 32605311, 2020). "There were additional correlations between TGFβ2 and the levels of CD8+T cell infiltration in 19 cancer types, CD4+T cell infiltration in 21 cancer types, macrophage infiltration in 23 cancer types, neutrophil infiltration in 23 cancer types, and dendritic cell infiltration in 23 cancer types." (PMID 32530106, 2020). "Moreover, addition of exogenous TGFβ2 abolished the inhibitory effect of imperatorin on cancer cell invasion and EMT, suggesting that TGFβ2 mediates the effect of imperatorin on cancer invasion." (PMID 32832354, 2020). "In stem cells and cancer cells, MMP2 and MMP9 are regulated by cytokines such as TGFβ2 and TNFα." (PMID 25774514, 2015). "We chose ERK, TGFB1, TGFB2, SIRT1, IL-6, PI3K, and WHSC1 (which were controlled by several genes) and three other genes AR, BCL-XL, and CCND1 that could mark the deterioration of the cancer, for testing." (PMID 26603105, 2015). "Furthermore, we observed that plastic EpCAMhigh and EpCAMlow cancer cells did not induce the expression of Tgfb1 and Tgfb2 compared with full epithelial cancer cells, ruling out autocrine activation of the TGFβ pathway in epithelial plastic cancer cells to acquire the mesenchymal state." (PMID 39075581, 2024). "Our data confirm the proliferative effect of TGFβ2 described in the literature but suggests that it drives the proliferation of STP cancer cells (or progenitor cells) as opposed to LTP cancer cells (aka cancer stem cells)." (PMID 21246056, 2011).